CD4 (CD4 molecule)
Diseases named in the same sentence as CD4 in open-access papers (continued):
Sharing a sentence is not in itself a finding about the gene and the disease.
COVID-19 (continued). "Regulatory T cells are responsible for the maintenance of the immune homeostasis, suppressing the activation, proliferation, and proinflammatory function of most lymphocytes, including CD4+ and CD8+ T cells, NK cells, and B cells (the latter two are known to be reduced in COVID-19 patients)." (PMID 32764275, 2020). "Examining the T cell responses of these patients, C97 had COVID-19 severity 9 without detectable antiviral CD4+ T cell or CD8+ T cell responses at day 13 PSO." (PMID 33010815, 2020). "To determine the changes in immune parameters of COVID-19 patients, we compared lymphocyte, CD3+CD4+T cell, CD3+CD8+T cell, CD19+B cell, CD16+CD56+NK cell count and CD4+T/CD8+T ratio between the date of hospital discharge and hospital admission or death in survivors and non-survivors." (PMID 33172355, 2020). "To see whether similar effects can be observed in COVID-19, we assessed the frequencies of the co-inhibitory receptors PD1, TIGIT, BTLA, LAG-3, and TIM-3 on CD8+ and CD4+ T cells in COVID-19 and malaria patients and compared them with healthy individuals." (PMID 32983106, 2020). "CyTOF has also been used to assess the efficacy of emerging forms of treatment for COVID-19, including mesenchymal stem cell transplantation, by precisely characterizing the different subsets of immune cells such as CXCR3+CD4+ T cells, CD8+ T cells, and NK cells." (PMID 32808850, 2020). "Other study showed that besides dramatically decreased numbers of total T cells, CD4+ and CD8+ T cell subsets, T cells from COVID-19 patients had significantly higher levels of the exhausted marker PD-1 (programmed cell death 1; CD279) compared to healthy controls." (PMID 32695683, 2020). "Peripheral blood analysis demonstrates significantly lower counts of CD4+ T, CD8+ T, and NK cells in PBMCs and increased expression of Programmed cell death protein 1 (PD-1) and Tim-3 on T cells and has been correlated with severity of COVID-19." (PMID 32781571, 2020). "Moreover, alterations in the relative frequency of several immune cell subsets has been reported, such as the reduction of CD4+ T cells, CD8+ T cells, B cells, and natural killer (NK) cells, an effect more prominent also in patients with severe COVID-19." (PMID 32512702, 2020). "Pathological findings had revealed that counts of peripheral CD4+ T and CD8+ T cells were substantially decreased in COVID-19 patients with ARDS, suggesting that SARS-CoV-2 may exert major impact on lymphocytes, especially T lymphocytes." (PMID 33180862, 2020). "Further characterization of CD4 T cells in unexposed individuals showed reactivity to an epitope of N protein that as high homology with N protein of MERS-CoV, OC43 and KHU1 and this is also present in individuals that recovered from SARS and COVID-19." (PMID 33133083, 2020). "The combination of CD4+ T cell count, NLR, and D-dimer, CT score, and CPIS could be used as COVID-19 disease severity predictors." (PMID 32985562, 2020). "In conclusion, current evidence suggests a significant negative association of peripheral lymphocyte levels with COVID-19 progression and mortality, but it was not significant in the subsets of CD3+ T cells, CD4+ T cells, CD8+ T cells, B cells, and NK cells." (PMID 33102499, 2020). "Of note, PLHIV with COVID-19 requiring hospitalization were more likely to have significantly lower median CD4 count than those hospitalized without COVID-19." (PMID 33748827, 2020). "This may explain the simultaneous attenuation of CRP and inflammatory cytokines (CD4( +) IFN-γ) in hemodialysis patients after calcitriol treatment, or elevation of both CRP and cytokines in severe COVID-19 patients." (PMID 32876941, 2020). "In severe COVID-19, the proportion of classical monocytes significantly increased whereas those of DCs, non-classical monocytes, intermediate monocytes, NK cells, EM-like CD8+ T cells, and EM-like CD4+ T cells significantly decreased." (PMID 32651212, 2020).
COVID-19 (continued). "Helper, suppressor, regulatory, CD4+ and CD8+ T cells are decreased; in fact, reduced functional diversity of T cells in peripheral blood may predict a severe progression in COVID-19 patients." (PMID 32764275, 2020). "In quantitative analysis of CD4+ and CD8+ T cells at different stages of maturity, it was found that compared with healthy subjects, the frequency of TEMRA (CD45RA+ CCR7−) and senescent CD8+ T cells (CD57 +) in COVID-19 patients was significantly higher." (PMID 32727485, 2020). "The proportions of IFNγ+CD4+ and IFNγ+CD8+ T cells and the titers of IgG, IgM, and IgA against SARS-CoV-2 spike protein increased and inversely correlated with the SARS-Cov-2 viral load in surviving hypertensive patients with severe COVID-19." (PMID 33362779, 2020). "The parameters included all antigen-specific CD4+ T cell, CD8+ T cell, and antibody measurements, plus general immune cell type measurements, plasma cytokines, age, comorbidities, and COVID-19 clinical disease severity." (PMID 33010815, 2020). "Interestingly, a recent study suggests that severely ill COVID-19 patients had lower levels of activated (CD11a+) and terminally differentiated (CD57+) peripheral blood CD4+ and CD8+ T cells (which are also S-protein reactive)." (PMID 33335518, 2020). "Some studies mentioned that CD4+T and CD8+T cells decreased in the COVID-19 patients." (PMID 33125396, 2020). "In this population of COVID-19 patients, the admission leukocyte count, neutrophil percentage and neutrophil count in those who died within 28 days were all higher than that of the survivors, and the lymphocyte count, CD3+ count and CD4+ count was lower." (PMID 33125396, 2020). "Longer quarantine periods might be more justified for COVID-19 patients with cough, higher levels of leucocytes, neutrophils and ESR and lower levels of CD3+CD4+ lymphocytes." (PMID 33256876, 2020). "However, consistent with total memory CD4+ and CD8+ T cells, CD8+ MAIT cells in some severe COVID-19+ individuals displayed greatly elevated expression of the various activation markers measured." (PMID 32669287, 2020). "CD4+ T lymphopenia (mean CD4+ counts < 384 cells/μl) was observed in 100% of the severe or critical cases of COVID-19 in weeks 1–4 compared to the lower limit of normal controls (RI2.5 = 384 cells/μl)." (PMID 33362779, 2020). "A survey done in patients in Wuhan reported no higher rates of COVID-19 in HIV-infected vs. non-HIV-infected people, and no increased risk with low CD4 cell count." (PMID 32574323, 2020). "Here, we measured SARS-CoV-2-specific antibodies (including neutralizing antibodies), SARS-CoV-2-specific CD4+ T cells, and SARS-CoV-2-specific CD8+ T cells in all individuals in a new cohort, with an emphasis on including acute cases across a range of COVID-19 disease severities." (PMID 33010815, 2020). "Altered characteristics of global CD4+ and CD8+ T cells in patients with severe COVID-19." (PMID 32937615, 2020). "By doing this the authors hoped to understand which antigens are targeted by CD4+ and CD8+ T cells, whether the corresponding antigens are the same or different, and how do they compare to the antigens currently considered for COVID-19 vaccine development." (PMID 32616709, 2020). "Together, our data revealed the preferential activation of CD4+ T cell responses but significant depletion of multiple innate-like T cell and CD8+ T cell subsets in peripheral blood as the featured T cell perturbations in severe COVID-19." (PMID 33101705, 2020). "SARS-CoV-2-specific CD4+ T cells were detected in almost all convalescent COVID-19 samples by AIM (14/15), with consistent responses against S, M, N, and MP_R, matching our previous cohort of convalescent COVID-19 cases." (PMID 33010815, 2020). "Gaining a deeper understanding of the role of neutrophil, CD4+ T cells, and B cells in the pathogenesis of SARS-CoV-2 infection could be important for the clinical management of COVID-19." (PMID 32492165, 2020).
COVID-19 (continued). "We further examined activation of specific memory CD4+ and CD8+ T cell subsets, where we found that many of the individual memory subsets expressed higher levels of activation markers selectively in the severe COVID-19 patients." (PMID 32669287, 2020). "In summary, comparing the expression of different co-inhibitory molecules in CD8+ and CD4+ T cells in COVID-19 vs. malaria, there is a transient increase of the expression of certain inhibitory receptors like LAG-3 and TIM-3 in COVID-19 in the overall context of acute immune activation." (PMID 32983106, 2020). "Gaining a deeper understanding of the role of neutrophils, CD4+ T cells, and B cells in the pathogenesis of SARS-CoV-2 infection could be important for the clinical management of COVID-19." (PMID 32492165, 2020). "A compromised immune system with a lower CD4+ T cells counts and elevated interferon levels in HIV infection might reduce clinical symptoms of COVID-19." (PMID 33384690, 2020). "When we analyzed correlation in each group we observed a significantly negative correlation between plasmablasts and CD4+ cells in COVID-19 X-ray (+) patients (R = −0.73, p < 0.05), without this correlation in COVID-19 X-ray (−) patients and healthy control." (PMID 33291439, 2020). "In addition, patients with COVID-19 exhibited significantly less surface HLA-DR on CD8+ T cells than patients with influenza and trends toward less HLA-DR on CD4+ T cells in comparison to both patients with influenza and healthy controls." (PMID 33187979, 2020). "The AUCs showed that the following could predict death due to COVID-19: leukocyte count; neutrophil percentage; neutrophil count; lymphocyte percentage; lymphocyte count; CD3+ %; CD3+ count; CD4+ %, CD4+ count and PaO2/FiO2." (PMID 33125396, 2020). "CD4+ and CD8+ T cells might play a key role in aggravating COVID-19 and predicts a more critical course in children." (PMID 32379199, 2020). "Our previous study similarly reported elevated GZMB and perforin expression in peripheral blood CD4+ T, CD8+ T, γδ T, and NK cells from COVID-19 patients with pulmonary sequelae, suggesting that increased cytotoxicity in peripheral blood T and NK cells may correlate with pulmonary damage." (PMID 40589761, 2025). "Similar observations were made in the acute phase frequency of CD4+ central and effector memory T cells, which were significantly lower in severe (hospitalised) versus mild (non-hospitalised) COVID-19 cases, whereas CD8+ compartment frequencies didn’t differ significantly between subgroups." (PMID 40242761, 2025). "Compared to people without HIV, PWH—especially those with low CD4 cell counts, uncontrolled viral loads, advanced or untreated HIV, and comorbidities—face a higher risk of severe illness, hospitalization, and mortality from COVID-19." (PMID 41214612, 2025). "Similarly, comparisons between COVID-19 survivors (Groups A, B, and C) and non-survivors (Group D) revealed a significantly lower expression of PD-1 on CD4+ T cells (p = 0.007) in survivors." (PMID 40005306, 2025). "To examine whether INR still mount antigen-specific CD4+ T cell immunity or not, we analyzed the breadth of the spike-specific CD4+ T cell repertoire after COVID-19 mRNA vaccination." (PMID 41212052, 2025). "Furthermore, our characterization of CD4+ T cells and CD8+ T cells revealed an increased percentage of early or late effector CD8+ T cells in pregnant SARS-CoV-2 infected women compared with post-COVID-19 pregnant women, consistent with a recent publication." (PMID 40661959, 2025). "However, COVID-19 vaccine trials included only small samples of virally suppressed PLWH on ART with normal CD4+ T cell counts, and did not consistently publish information on immunogenicity in PLWH." (PMID 40432125, 2025). "However, we did not observe a significant effect of COVID-19 vaccination, ART, CD4+, or HIV viral load on the risk of Omicron infection." (PMID 41268402, 2025).
COVID-19 (continued). "In addition, COVID-19 vaccine may induce suboptimal immune responses in PWH due to persistent immune dysfunction and exhaustion, even after HIV suppression and CD4 cell restoration with ART." (PMID 39772028, 2024). "It seems that the HLA restricted CD4+ as well as CD8+ T-cell epitopes are comprehensively distributed in the whole SARS-CoV-2 proteome, therefore, the induction of broadly protective cellular responses is a feasible strategy to enhance the effectiveness of COVID-19 vaccines." (PMID 39257586, 2024). "The asymptomatic infections in unvaccinated COVID-19 patients might be attributed to homing and redistribution of high numbers of functional CCCs/SARS-CoV-2 cross-reactive CD4+ and CD8+ T cells into the lungs of unvaccinated asymptomatic COVID-19 patients, rather than in peripheral blood." (PMID 38605956, 2024). "In COVID-19 patients with severe respiratory failure (SRF), either macrophage-activation syndrome or a marked reduction in human leukocyte antigen-D related (HLA-DR) expression, along with a profound depletion of CD4 lymphocytes, CD19 lymphocytes, and natural killer (NK) cells, has been observed." (PMID 39679195, 2024). "Also, the expression of PD-1 and TIGIT on CD4+ T cells did not correlate with the level of humoral and cellular response against COVID-19." (PMID 39355257, 2024). "Yet, we did not confirm that a higher peripheral CD4/CD8 T-cell ratio was associated with a better outcome, and whether peripheral CD4/CD8 T-cell ratio reflects prognosis in COVID-19 deserves further studies." (PMID 38915768, 2024). "Notably, in patients with severe COVID-19, the proportion of PD-1 positive CD4 cells was elevated over those in the non-severe group and HCs at 2-4 weeks (P < 0.05 and P < 0.01, respectively)." (PMID 39355257, 2024). "The updated ‘WHO SAGE roadmap on uses of COVID-19 vaccines in the context of OMICRON and substantial population immunity’ (30 March 2023) places PWH in the ‘high priority’ group for vaccination if they have a CD4 count <200 cells/mm3, unsuppressed/detectable viral load or an opportunistic infection." (PMID 37821620, 2024). "Thus, early SARS2-specific CD4+ and CD8+ T cell responses were specifically associated with reduced upper airway SARS2 viral loads in unvaccinated, nonhospitalized cases of acute COVID-19." (PMID 39704169, 2024). "Early infection is typically characterized by viral pneumonia of varying severity, which may progress to COVID-19-related acute respiratory distress syndrome (ARDS) with a predominance of CD-3+ and CD-4+ T lymphocytes in precapillary and postcapillary blood vessels." (PMID 40012912, 2024). "Therefore, the next generation of COVID-19 vaccines should also target other highly conserved structural and non-structural SARS-CoV-2 antigens capable of inducing protection by cross-reactive CD4+ and CD8+ T cells." (PMID 38318166, 2024). "An increased proportion of cytotoxic CD4+ T helper (CTL-TH) cells and follicular TFH-cells (which have a role in B-cell affinity maturation and antibody production) were seen in hospitalized patients with COVID-19 relative to regulatory T-cell (Treg) populations." (PMID 40012912, 2024). "Next, we determined whether the CCCs/SARS-CoV-2-cross-reactive epitopes were cross-recognized preferentially by the CD4+ and CD8+ T cells from either unvaccinated asymptomatic COVID-19 patients, or unvaccinated severely ill COVID-19 patients and unvaccinated patients with fatal outcomes." (PMID 38605956, 2024). "However, in another group of COVID-19 infected patients, the CD4 + /CD8 + T cell ratio may also be elevated due to a more pronounced reduction in CD8+ T cells than in CD3+, CD4+ and CD8+ T lymphocytes." (PMID 38811907, 2024).
COVID-19 (continued). "Emerging evidence demonstrated that COVID-19 vaccination in the ipsilateral arm was immunogenically superior to the contralateral arm vaccination in the neutralizing activity of anti-S IgG, median spike-specific CD8 T-cell levels, and CTLA-4 expression on spike-specific CD4 T-cells." (PMID 38250886, 2024). "The viewpoint that low CD4 counts may not induce the robust inflammatory response and further reduce clinical symptoms and poor clinical outcomes of COVID-19 has been reported by some studies." (PMID 39127636, 2024). "In this study, we recruited PWH with median time of HIV-1 infection of 6 years, median CD4/CD8 ratio of 1.0, good adherence to ART, persistently undetectable viral load, and negative serology against SARS-CoV-2, who then received the complete vaccination schedule against COVID-19." (PMID 38812512, 2024). "Here, we investigated the dynamic changes of CD3−CD19+B cells, T cell subsets (CD3+CD4+ T cells, CD3+CD8+ T cells, DN T cells and Tregs), and CD3−CD16+CD56+ natural killer (NK) cells during both the acute infective and convalescent periods in patients with mild, severe, and critical COVID-19." (PMID 39650838, 2024). "Indeed, recent findings provided some evidence for the possible capacity of SARS-CoV-2 to infect blood-circulating leukocytes in COVID-19 patients, while SARS-CoV-2-positive monocytes, B cells, and CD4+ T lymphocytes were also detected in postmortem lung tissue." (PMID 38787201, 2024). "Migrants also exhibit higher rates of late HIV diagnosis and loss to care compared to native-born populations in their host countries, leading to negative impacts on HIV viral suppression and CD4 cell levels, both identified as predictors of severe COVID-19 outcomes." (PMID 38221982, 2024). "A significantly lower CD4/CD8 ratio was found in severe or fatal ASyS+COVID compared to non-ASyS IIM donors with moderate COVID-19, suggesting that the prominent loss of CD4+ T cells and relative expansion of CD8+ T cells is a distinct feature of high-risk ASyS suffered from COVID-19." (PMID 38500883, 2024). "Additionally, during the onset of COVID-19, organisms such as Blautia obeum, Coprococcus catus, and C. comes can facilitate an increase in the proportion of other specific immune cells types, such as the CD3+ T-cells, CD4+ T-cells, and CD8+ T-cells." (PMID 38863829, 2024). "The presence of CD4+ and CD8+ T cells may indicate a protection against COVID-19, considering that SARS-CoV-2 patients with SARS-CoV-2 vaccine have the so-called hybrid immunity (HI) (infection plus vaccination), and experience reduced severity and fewer hospitalizations upon reinfection." (PMID 38651389, 2024). "In this study, despite the low number of CD4+T cells, no severe clinical symptoms of active toxoplasmosis (lymphadenopathy, chorioretinitis and cerebral/pulmonary manifestations) were detected in COVID-19 patients infected with high titer of T. gondii IgG." (PMID 38172676, 2024). "Indeed, while COVID-19 vaccines typically induce potent T-cell responses in PLWH, the frequency of spike-specific CD4+ T cells following COVID-19 vaccination may be lower in PLWH, particularly among those with low CD4+ T-cell counts." (PMID 38793543, 2024). "Inhibitory receptor molecules, such as CD223, highly expressed in CD4+ T-cells, and PD-1, expressed by CD4+ and CD8+ T-cells in peripheral blood cells from patients progressing to death, indicated that SARS-CoV-2 triggers immune escape by inducing T-cell exhaustion during severe COVID-19." (PMID 39597661, 2024). "The CDC currently recommends that all PLH, regardless of CD4 count, receive the two-dose primary series of mRNA COVID-19 vaccination given 3–8 weeks apart, followed by a booster vaccination dose as recommended by the Advisory Committee on Immunization Practices (ACIP)." (PMID 39066418, 2024).